BCAT2 (branched chain amino acid transaminase 2)
Description:
Catalyzes the first reaction in the catabolism of the essential branched chain amino acids leucine, isoleucine, and valine. Branched chain amino acid catabolism plays a role in adipocyte differentiation by providing lipogenic acetyl-CoA pools in differentiated adipocytes (By similarity). Mechanistically, acetyl-CoA derived from branched chain amino acid catabolism is used by EP300/p300 to acetylate and inhibit PRDM16, thereby preventing adipose tissue browning (By similarity). May also function as a transporter of branched chain alpha-keto acids (By similarity).
Synonyms: PP18; BCATM; BCT2; BCAM; HVLI
Tractability: Small molecule: a structure with a bound ligand is known; a high-quality ligand is known; it has a high-quality binding pocket. PROTAC: ubiquitination databases record sites on it; its protein half-life has been measured; a small molecule that binds it is known.
Target class: Enzyme; Transferase
Chemical probes: BAY-069 (high quality)
Gene: Protein-coding gene on chromosome 19 (48,795,061 to 48,811,056, reverse strand). Ensembl gene ENSG00000105552.
Subcellular location: Mitochondrion
Subcellular location (Human Protein Atlas): Mitochondria; Nucleoplasm
Pathways (Reactome):
Metabolism: Branched-chain amino acid catabolism
Gene Ontology:
Molecular function: branched-chain-amino-acid transaminase activity; L-isoleucine-2-oxoglutarate transaminase activity; L-leucine-2-oxoglutarate transaminase activity; L-valine-2-oxoglutarate transaminase activity; protein binding; catalytic activity
Biological process: branched-chain amino acid catabolic process; branched-chain amino acid biosynthetic process; brown fat cell differentiation; L-isoleucine catabolic process; L-valine catabolic process; negative regulation of brown fat cell differentiation; branched-chain amino acid metabolic process; energy homeostasis; L-leucine catabolic process
Cellular component: mitochondrion; mitochondrial matrix
Genetic constraint (gnomAD): Loss-of-function variants: 45 observed, 55.6 expected, observed/expected ratio (o/e) 0.81, 90% interval 0.64 to 1.04. The upper end of that interval is the gene's LOEUF score, 1.04, which puts it in group 4 of 6, group 1 being the genes least tolerant of losing a copy. Missense variants: 478 observed, 528.7 expected, observed/expected ratio (o/e) 0.9, 90% interval 0.84 to 0.98. Synonymous variants: 215 observed, 221.89 expected, observed/expected ratio (o/e) 0.97, 90% interval 0.87 to 1.09.
Gene-disease validity (ClinGen):
ClinGen rates the evidence that BCAT2 causes each of these diseases.
hypervalinemia and hyperleucine-isoleucinemia (autosomal recessive): Definitive. Elevated levels of plasma valine and leucine/isoleucine levels, associated with symptoms of headache and mild memory loss and attributed to biallelic variants in the BCAT2 gene.
Homologues: Orthologues: chimpanzee BCAT2 (97% identical), macaque BCAT2 (93% identical), dog BCAT2 (86% identical), mouse Bcat2 (83% identical), guinea pig BCAT2 (83% identical), pig BCAT2 (81% identical), rat Bcat2 (81% identical), zebrafish bcat2 (62% identical), rabbit BCAT2 (61% identical), tropical clawed frog bcat2 (59% identical), Drosophila melanogaster Bcat (48% identical), Caenorhabditis elegans bcat-1 (47% identical), and 1 more. Paralogues in human: BCAT1 (55% identical).
Diseases named in the same sentence as BCAT2 in open-access papers:
BCAT2 is named in the same sentence as 71 diseases in open-access papers, as found by Europe PMC text mining. Sharing a sentence is not in itself a finding about the gene and the disease. The quoted sentences say what the papers report.
pancreatic cancer (15 papers, 2019 to 2025). "Elevated BCAT2 expression in liver and pancreatic cancers is associated with reduced ferroptosis-related cell death." (PMID 40438606, 2025). "In humans, altered expression of BCAT2 is implicated in tumor growth and nucleotide biosynthesis in some forms of pancreatic cancer." (PMID 30845962, 2019). "We have verified that BCAT2, as a crucial enzyme implicated in mediating sulfur amino acid metabolism, regulates intracellular glutamate levels, and its specific expression shields liver cancer and pancreatic cancer cells from ferroptosis." (PMID 41431044, 2025). "Recent studies have shown that compared to normal tissues, BCAT2 expression is elevated in cancers such as bladder cancer, pancreatic cancer, breast cancer, and non-small cell lung cancer (NSCLC)." (PMID 40438606, 2025). "A BCAAS-rich diet promotes pancreatic cancer development through USP1-mediated BCAT2 stabilization, and BCAAS intake is positively correlated with pancreatic cancer risk." (PMID 40438606, 2025). "BCAT2 levels are higher in pancreatic cancer cell lines compared to normal cell lines, making it a potential clinical target for pancreatic cancer therapy." (PMID 40438606, 2025). "The overexpression of BCAT2 in the human pancreatic cancer cell line Aspc-1 and hepatocellular carcinoma cells HepG2 increased intracellular glutamate and glutamate release, increased system Xc− activity, and inhibited ferroptosis." (PMID 38028625, 2023). "Collectively, these data indicate that K44 mutants stabilize BCAT2 and promote pancreatic tumor cell growth upon BCAA deprivation both in vitro and in vivo." (PMID 32467562, 2020). "To also explore the effect of BCAT2 acetylation on pancreatic cancer cell proliferation in vivo, we performed xenograft experiments using stable BCAT2 WT and K44R mutant cells." (PMID 32467562, 2020). "Furthermore, ferritin phagocytosis and subsequent activation of the AMPK pathway can suppress the expression of BCAT2 in the pancreatic cancer cell line AsPC-1, suggesting that AMPK plays a dual role in ferroptosis." (PMID 38268915, 2023). "Moreover, BCAT2 was identified as a specific inhibitor of ferroptosis by the mechanism of regulating intracellular glutamate levels in liver and pancreatic cancer cells." (PMID 35326233, 2022). "Furthermore, BCAT2 expression, which was required for collateral lethality caused by deletion of PDAC malic enzyme, was significantly downregulated in pancreatic cancer with increased malice two gene deletion." (PMID 36119495, 2022). "Moreover, our experiments confirmed that the expression level of BCAT2 is regulated by AMPK-SREBP1 signaling pathway, which is supported by previous finding that genomic deletion of BCAT2 confers collateral lethality in pancreatic cancer." (PMID 33097833, 2021). "To investigate whether BCAT2 acetylation is important for pancreatic cancer cells, we examined the effect of BCAT2 acetylation on pancreatic cancer cells." (PMID 32467562, 2020). "Therefore, BCAT2 may also provide a new therapeutic target for pancreatic cancer, presumably use of the modified BGAT may help the treatment of cancer." (PMID 38028625, 2023). "Acetylating lysine 44 (K44), an evolutionarily relatively conserved residue located at the N-terminus of BCAT2, of BCAT2 promotes BCAT2 degradation and inhibits BCAA catabolism and pancreatic cancer growth." (PMID 38028625, 2023). "On the basis of the data showing that BCAA deprivation promotes BCAT2 degradation in vitro, we used the 1/5 BCAA to manipulate the BCAA-deprivation condition and observed the effect of K44 acetylation on BCAT2-induced pancreatic tumor cell growth in vivo." (PMID 32467562, 2020). "To check the correlation between BCAT2 and its acetyltransferase or deacetylase, we analyzed the correlation between CBP and BCAT2 expression in pancreatic cancer patients in a TCGA cohort and found that BCAT2 was negatively correlated with CBP." (PMID 32467562, 2020).
pancreatic cancer (continued). "BCAT2 acetylation suppresses BCAA catabolism and pancreatic tumor growth." (PMID 32467562, 2020). "In addition, BCAT2 has been found to be acetylated on lysine 44 and utilize the ubiquitin-proteasome pathway to accelerate its degradation, resulting in decreased BCAA catabolism, thereby inhibiting pancreatic tumor growth." (PMID 36119495, 2022). "However, targeted drugs for BCAT2 are still lacking, the tracing of the diets of pancreatic cancer patients at an early stage still needs further study, and direct evidence to prove that dietary BCAA promotes PDAC progression in vivo needs to be addressed." (PMID 35663242, 2022).
Insulin resistance (12 papers, 2014 to 2025). Increased resistance towards insulin, that is, diminished effectiveness of insulin in reducing blood glucose levels. "Another study suggests that the use of l‐leucine metabolites improves insulin resistance in BCAT2‐depleted cells in skeletal muscle." (PMID 40810552, 2025). "Conversely, a recent study indicates that white adipose tissue-specific Bcat2 knockout mice display resistance to high-fat diet-induced obesity and insulin resistance, attributed to enhanced browning and thermogenesis in white adipose tissue." (PMID 39007094, 2024). "If elevated BCKA levels are indeed the main driver of insulin resistance, then lowering them can be accomplished through BCAT2 inhibition or BCKDK inhibition." (PMID 39007094, 2024). "Although not consistent across all reports, the studies reviewed suggest a reduction in BCAT2 level in diabetes/insulin resistance." (PMID 34354601, 2021). "However, at the protein level, insulin resistance significantly reduced BCAT2 expression, the initial step in BCAA metabolism." (PMID 40422898, 2025). "In support of this hypothesis, mice with whole-body Bcat2 deletion exhibit elevated plasma BCAAs and decreased BCKAs, yet remained protected from high-fat diet-induced obesity and insulin resistance." (PMID 39007094, 2024). "Furthermore, supplementation of BCKAs in white adipose tissue-specific Bcat2 knockout mice reverses these favorable effects, leading to the reinstatement of obesity and insulin resistance." (PMID 39007094, 2024). "Thus, elevation in circulating BCAAs in obesity/insulin resistance states cannot be totally explained by changes in the expression of BCAT2." (PMID 34354601, 2021). "Conversely, targeting BCAT2 in white adipose tissue leads to increased BCAA levels while concurrently reducing BCKAs, thus mitigating insulin resistance." (PMID 39007094, 2024). "BCAT2 is inhibited by oxidative stress and high NADH/NAD+ ratio, both present in insulin resistance." (PMID 35742839, 2022). "Finally, in rats fed fructose for 45 days to produce a non-obese insulin resistance state, there were reductions in muscle BCAT2 activity (15%), even though activities of the enzyme in liver and adipose tissue were not affected." (PMID 34354601, 2021). "Finally, the Bcat2 knockout mice actually display improvements in insulin resistance rather than its exacerbation." (PMID 25050624, 2014). "Interestingly, although mice lacking BCAT2 have elevated BCAA levels, they did not manifest insulin resistance." (PMID 33400857, 2021).
pancreatic ductal adenocarcinoma (12 papers, 2018 to 2026). An infiltrating adenocarcinoma that arises from the epithelial cells of the pancreas. "And the expression of BCAT2 is enhanced in mouse models and human pancreatic ductal adenocarcinoma (PDAC)." (PMID 41457818, 2026). "TRIM21 mediates the degradation of branched-chain amino acid transaminase 2 (BCAT2) to inhibit the formation and progression of pancreatic ductal adenocarcinoma." (PMID 39154024, 2024). "BCAT2 protein levels were significantly elevated in human pancreatic ductal adenocarcinoma (PDAC) cells, and BCAT2 knock down significantly inhibited the proliferation of PDAC cells." (PMID 38028625, 2023). "BCAT2-mediated branched-chain amino acid (BCAA) catabolism is critical for pancreatic ductal adenocarcinoma (PDAC) development, especially at an early stage." (PMID 35663242, 2022). "BCAT2 enhances BCAA uptake to sustain BCAA catabolism and mitochondrial respiration in the development of pancreatic ductal adenocarcinoma." (PMID 40032645, 2025). "In pancreatic ductal adenocarcinoma (PDAC), the metabolism of Ala, Pro, Gln, Asp and Ser, as well as BCAT2-mediated branched-chain amino acid (BCAA), has been usurped for malignant progression." (PMID 35663242, 2022). "Overexpression of the mutant form of the proto-oncogene GTPase KRAS (KRASG12V) in pancreatic ductal adenocarcinoma (PDAC) samples increases, whereas knockdown of KRAS decreases, BCAT2 protein, with a minimal effect on BCAT2 mRNA level." (PMID 34354601, 2021).
Obesity (11 papers, 2012 to 2024). Accumulation of substantial excess body fat. "This new mechanism linking BCAAs to pro-arrhythmia may not only be relevant for inherited BCAT2 deficiency, but also for acquired metabolic disorders such as diabetes, obesity, and heart failure in which BCAA metabolism is impaired." (PMID 34142125, 2022). "Adipose tissue Bcat2 KO mice exhibit increased iWAT browning and thermogenesis, and have an increased ability to resist high-fat diet-induced obesity." (PMID 39351529, 2024). "As a key enzyme in the catabolism process of BCAAs, previous researches mainly focused on metabolic‐related role of BCAT2 in the diseases, such as obesity, diabetes and arrhythmia." (PMID 36642843, 2023). "BCKA supplementation rescues Bcat2 KO mice from high-fat diet-induced obesity." (PMID 39351529, 2024). "In subjects with obesity, BCAT2 and BCKDH expression is reduced mainly in visceral adipose tissue." (PMID 37571315, 2023). "Branched-chain amino acids (BCAAs) are associated with the progression of obesity-related metabolic disorders; additionally, BCAA catabolism is suggested to play a role in the pathogenesis of metabolic disturbances, and BCAT2 is an important enzyme that catalyzes the initial step of BCAA catabolism." (PMID 37108768, 2023). "Increased BCAT2 mRNA expression in the AA was also correlated with reduced KIV/Val ratio suggesting an increased mRNA expression of BCAA metabolizing enzymes drives BCAA catabolism in the AA tissues of patients with obesity undergoing cardiac surgery." (PMID 32903728, 2020). "Nevertheless, further research is needed to clarify the mechanisms responsible for the decreased expression and activity of BCAT2 and BCKDH in adipose tissue during obesity." (PMID 37571315, 2023). "Branched-chain aminotransferase 2 (BCAT2), an isoform of BCAT found in mitochondria, and BCKDH activity are reduced in the adipose tissue of mice and rats with genetic or diet-induced obesity." (PMID 37571315, 2023). "Increases in the mRNA levels of ACADSB, BCAT2, HADHA and both the A and B subunits of BCKDH suggested that BCAA catabolism is upregulated in the AA of obese cardiac surgery patients and particularly pronounced in class III obesity." (PMID 32903728, 2020).
breast carcinoma (6 papers, 2017 to 2024). "BAY-069, targeting both BCAT1 and BCAT2, has exhibited significant antiproliferative effects on glioblastoma cells and breast cancer cells." (PMID 39143065, 2024). "BCAT1 expressed in the cytoplasm was highly expressed in human epidermal growth factor receptor 2 positive (HER2+) breast cancer, while BCAT2 expressed in the mitochondria tended to be highly expressed in estrogen receptor-positive (ER+) breast cancer." (PMID 37699892, 2023). "The suitability of silencing one of this enzymes (branched chain amino acid transaminase 2; BCAT2) with therapeutic effects was tested experimentally on the breast cancer cell line MCF-7 and primary cell culture of breast tumor (BCC), leading to lower cell proliferation." (PMID 28798381, 2017). "BCAT2 was upregulated in PDAC, luminal type breast cancer, NSCLC, while it was downregulated in HCC." (PMID 34526485, 2021).
diabetes (6 papers, 2012 to 2026). "As expected, alizarin red S staining and micro-CT analysis also revealed that VSMC-specific BCAT2 deficiency reduced aortic calcification in diabetic plaque, and this result was further confirmed by H&E and von Kossa of the aortic root and aortic arch sections." (PMID 41503231, 2026). "H&E and von Kossa staining of the aortic root and aortic arch sections also suggested that knockdown of BCAT2 could significantly decrease calcification in diabetic plaque." (PMID 41503231, 2026). "BCAT2-mediated histone propionylation up-regulated RUNX2 expression, resulting in VSMC osteoblastic differentiation and the development of VC in diabetic plaques." (PMID 41503231, 2026). "Compared with the normal control (NC) group, the BCAT2 protein level was significantly increased in the diabetes mellitus (DM) group, but the BCAT1 protein level had no significant change." (PMID 41503231, 2026). "Mechanistically, BCAT2-mediated BCKA-derived prop-CoA generation promotes propionylation at lysine 23 of histone H3 (H3K23pr), which contributes to the activation of RUNX2 expression, thereby accelerating VSMC osteoblastic differentiation and VC in diabetic plaques." (PMID 41503231, 2026).
hepatocellular carcinoma (6 papers, 2021 to 2025). A malignant tumor that arises from hepatocytes. "Here, by using a high-throughput CRISPR/Cas9-based genetic screen in HepG2 hepatocellular carcinoma cells to search for metabolic proteins inhibiting ferroptosis, we identified a branched-chain amino acid aminotransferase 2 (BCAT2) as a novel suppressor of ferroptosis." (PMID 33097833, 2021). "In hepatocellular carcinoma, AMPK activation by ferroptosis inducers like erastin, sorafenib, and sulfasalazine inhibits branched chain amino acid transaminase 2 (BCAT2) transcription, modulating glutamate levels and preventing ferroptosis." (PMID 39935430, 2025). "In hepatocellular carcinoma cells (HepG2), ferroptosis inducers (sulfasalazine, sorafenib, and erastin) activated ferritinophagy and increased cellular Fe2+ levels, consequently activating AMPK phosphorylation and suppressing nuclear translocation of SREBP1, then inhibiting BCAT2 transcription." (PMID 37522124, 2023). "In addition, the expression of the BCAA degradation pathway in extrahepatic cholangiocarcinoma and gallbladder cancer was similar to the expression in ICC, and in hepatocellular carcinoma (HCC), both BCAT1 and BCAT2 were highly expressed in tumour samples as previously reported." (PMID 37076565, 2023).
type 2 diabetes (6 papers, 2017 to 2023). "When compared to BMI-matched obese controls, type 2 diabetes is characterized by reduced expression of genes encoding for the mitochondrial steps of BCAA metabolism BCAT2, and BCKDHB (encoding the E1beta subunit of BCKD)." (PMID 29062026, 2017). "Early-onset type 2 diabetes was characterized by reduced expression of BCAT2." (PMID 29062026, 2017). "Moreover, insulin modulates BCAA transamination in type 2 diabetes and BCAT2 activity, suggesting that insulin resistance could lead to an accumulation of BCKAs due to defects in both BCAA transamination and oxidation." (PMID 34131782, 2021). "Expression of genes encoding enzymes involved in the first steps of BCAA metabolism, namely branched-chain amino acid transaminase 2 (BCAT2) and three subunits of the BCKDH complex were decreased in skeletal muscle of individuals with type 2 diabetes." (PMID 34131782, 2021). "Notably, BCAT2, CD44 and HIF1A were directly related to the pathway of maturity onset diabetes of the young." (PMID 37904700, 2023). "Our data indicate that diabetic db/db mice may be a good model of type 2 diabetes, and are characterized by reduced muscle BCAA degradation due to a lower level of BCKDHA subunit complex, and increased levels of the transaminase (BCAT2)." (PMID 29062026, 2017).